CDK2 (cyclin dependent kinase 2)
Diseases named in the same sentence as CDK2 in open-access papers (continued):
Sharing a sentence is not in itself a finding about the gene and the disease.
cancer (continued). "As earlier reported, circ-Foxo3 expression was downregulated in several cancer cells than in non-cancer cells, and overexpressed circ-Foxo3 inhibited cell proliferation through binding to CDK2 and p21." (PMID 28219405, 2017). "Finally, we describe how the MYC/CDK2/p27/SKP2 axis impacts on tumor development and discuss possible ways to interfere therapeutically with this system to improve cancer treatment." (PMID 28665315, 2017). "From the point of view of cancer or tumor research, it was reported that miR-103 is part of the G1/S transition regulatory network, by targeting CCNE1, CDK2, and CREB1 (cAMP responsive element binding protein 1) during IGF-1 simulated proliferation in mouse crypt cells." (PMID 26935418, 2016). "Also known as CYC202 or seliciclib, this purine analog primarily inhibits CDK2 and CDK5, as well as CDK1, CDK7 and CDK9 in several forms of human cancers." (PMID 25625291, 2015). "Dinaciclib (SCH 727965, Merck) is a pyrazolo [1,5-α]pyrimidine that potently inhibits CDK1, CDK2, CDK5, and CDK9 with IC50 values ranging from 1 to 4 nM in a broad spectrum of human cancer cell lines including MCL, NHL, leukemia, colon, pancreatic, breast, prostate, SCLC, liver, and bladder." (PMID 25914884, 2015). "CDK2 and CCNE1 were increased in carcinomas showing that these use the opposite way to control RB1." (PMID 26008974, 2015). "Given that CCNE1 silencing in cancer cells harbouring CCNE1 gene amplification leads to G1 arrest, we tested whether these cells would be dependent on CDK2 expression and kinase activity for their survival." (PMID 22433433, 2012). "MF growth inhibited all cancer cell lines regardless of tissue of origin and hormone responsiveness, and reduced the activity of Cdk2." (PMID 21619605, 2011). "Deregulation of Cdk4 is widespread in human cancer, CDK4 gene knockout is highly protective against chemical and oncogene-mediated epithelial carcinogenesis, despite the continued presence of CDK2 and CDK6; and overexpresssion of Cdk4 promotes skin carcinogenesis." (PMID 21668989, 2011). "In order to determine whether this was also the case in the A2780 cancer cell line, p27 was immunoblotted in total CDK4 and CDK2 complexes isolated by immunoprecipitation from untreated cells." (PMID 17088910, 2006). "Luteolin prevents cancer via modulation of numerous pathways, that is, by inactivating proteins; such as procaspase‐9, CDC2 and cyclin B or upregulation of caspase‐9 and caspase‐3, cytochrome C, cyclin A, CDK2, and APAF‐1, in turn inducing cell cycle arrest as well as apoptosis." (PMID 39830909, 2025). "Since we found that CDK2 antagonism opposed centrosome clustering, combining such an inhibitor with a PLK4 inhibitor that we reported to promote supernumerary centrosomes could reduce proliferation and augment apoptosis in polyploid cancer cells." (PMID 40232858, 2025). "Intriguingly, the gene expression levels of BCL2, CDK2, MDM2, Casp9 and P21 were reversed in HeLa cells treated with L. cornuta ethyl acetate fraction when compared with the untreated HeLa cells, indicating its potential to regulate cell proliferation, apoptosis, and cell cycle in cancer cells." (PMID 39005932, 2024). "Indeed, engineered CDK2, but not CDK9 over-expression, reversed the presence of cancer cells having multipolar mitoses or chromosome ring formations after treatment with CYC065 or transfection of siRNAs that targeted CDK2." (PMID 38031910, 2023). "MYC, CDK2, and cyclin D1 (highlighted by red circles) as part of the CCT2 interactome are shown, supporting that CCT2 could be a central point or node for regulation of cancer proliferation pathways mediated by these factors." (PMID 33996588, 2021). "We propose that a CDK2/4/6 triple-inhibitor may offer some advantages over CDK4/6 dual-inhibitor in providing broader patient selection, higher efficacy, and broader types of cancers for treatment." (PMID 33579185, 2021).
cancer (continued). "For instance, CDK2 knockout mice remain viable without apparent abnormalities which suggests that CDK2 inhibitors might selectively kill cancer cells without being toxic to normal cells." (PMID 33805800, 2021). "We analyzed CAF correlations with expression profiles of STAT3/CDK2/4/6 and found that out of the 40 TCGA cancer types analyzed via the TIMER server, CAF and STAT3 expressions were correlated in cohorts of 36 cancers types, while CAF and CDK6 expressions were correlated in 34 cancer types." (PMID 33668805, 2021). "Thus, our study showed that the STAT3/CDK2/4/6 signature not only regulates immune cell infiltration but also affects the benefit for cancer patients of immune checkpoint blockade and provides a rationale for the combination of STAT3/CDK2/4/6 antagonist and immunological checkpoint inhibitors." (PMID 33668805, 2021). "That is, cancer cells exiting mitosis with low levels of CDK2 (quiescent cells) would strictly depend upon CDK4/6 function to re-enter the cell cycle, whereas cells exiting mitosis with high levels of CDK2 (proliferating cells) would bypass the requirement for CDK4/6 activity." (PMID 33239679, 2021). "Therefore, we hypothesized that combined inhibition of CDK4/6 and CDK2 might inhibit overexpressed C-MYC and hTERT sequentially, thereby inducing senescence and preventing cancer progression." (PMID 33260316, 2020). "Similarly, AdE downregulated CDK2; upregulated PARP in HepG2, HCT-116, and MCF-7 cancer cells; upregulated caspase-3; inducted G0/G1 cell cycle arrest; and inducted apoptosis at the pre-G1 phase in HepG2 cancer cell line." (PMID 33294124, 2020). "It appears that silibinin was also able to decrease the kinase activities of Cdk2 and 4 and at the inverse to increase Cdk inhibitors that control negatively Cdk-cyclin complexes such as Kip1/p27, Cip1/p21 and p18/INK4C in in vitro and in vivo in various cancers." (PMID 32344919, 2020). "Some studies have shown that CDKN3 acts as a cancer-promoting gene in a variety of ways to regulate the G1/S phase transition, while others have reported that CDKN3 plays an anti-tumour role via dephosphorylation of CDK2, thereby inhibiting the G1/S phase transition." (PMID 32000807, 2020). "For these tumor types, five cancer drivers were targeted only by NPs at < 100 nM, including Adenylate Cyclase 1 (ADCY1), Matrix Metallopeptidase 2 (MMP2), Aryl Hydrocarbon Receptor (AHR), Cyclin Dependent Kinase 2 (CDK2), and Mitogen-Activated Protein Kinase 11 (MAP3K11)." (PMID 31214023, 2019). "Although no direct MYBL2 inhibitor is available yet, CDK2 inhibition could be used to reduce MYBL2 activity in MYBL2 high-expressing cancers." (PMID 28640249, 2017). "We suggest that specific Cdk2 inhibitors should not be toxic to normal dividing cells but they might promote senescence of cancer cells when combined with DNA damaging agents." (PMID 29044141, 2017). "CDK2 siRNA did not induce cell apoptosis in any of the cell lines tested (data not shown), which was in agreement with the previous observation of lack of cell death after CDK2 inhibition in several cancer cell types." (PMID 24444383, 2014). "Thus, development of CDK2 and CDK9 inhibitors may also be useful for the development of cancer drugs." (PMID 23140174, 2012).
cancer (continued). "Consistently, cancer-associated genes that had not been previously associated to AP-2 were identified in the tumor extracts datasets, as for instance the breast cancer susceptibility gene 2 (BRCA2) and the cyclin-dependent kinase 2 gene." (PMID 21876733, 2011). "Recent findings, however, suggest that CDK2 may not be a key cell cycle player and question whether selective CDK2 inhibition is a useful cancer therapy strategy." (PMID 19684852, 2009). "Similarly, the CDK2/CDK9 inhibitor CYC065 (Cyclacel) was found to induce mitotic catastrophe in CIN+ cancer cells, restraining tumour growth and underscoring its potential to treat cancers that display high-grade aneuploidy and substantial intratumoural karyotype heterogeneity." (PMID 38067140, 2023). "A highly specific CDK2 inhibitor is not yet commercially available, although one compound, namely PF-07104091, is under investigation in a phase I clinical study as a single agent, and in combination therapy for several cancer types, including TNBC (clinicaltrials.gov identifier: NCT04553133)." (PMID 35884422, 2022). "The anti-cancer effects of lipid-soluble vitamins in various GBM cell lines are attributed to a diverse range of molecular mechanisms through changes in the expression of a wide range of biomarkers, of which CDK2, GFAP, p27, Bax, and CASP8 genes may have some clinical value." (PMID 35889829, 2022). "Furthermore, statins could possibly induce apoptosis in cancer cells independent of their effect on cholesterol levels by suppressing cyclin−dependent kinase 2 (CDK2) or activating caspases and promoting cell-cycle arrest in PCa." (PMID 35615153, 2022). "Taking together, these results not only pointed out the potential roles of aberrant CDK2/4/6 expression in the initiation and development of multiple cancer but also suggest that STAT3 and CDK2/4/6 expression may alter tumor immune microenvironment and hence involved in cancer immune responses." (PMID 33668805, 2021). "For this reason, CDK2 may not be essential in some cancer cells." (PMID 30959874, 2019). "A requirement for the FPPRGPRPVQSV region of Cdk4 to provide energy for cancer cell division could also provide an explanation for the fact that Cdk4 rather than Cdk2 or Cdk6 appears to be the mandatory cyclin-dependent kinase for carcinogenic malignant transformation." (PMID 21668989, 2011). "Therefore, inhibitors of CDK2 may not be appropriate for cancer therapy and more efforts are focused on inhibition of cyclin A2 and/or cyclin A2- CDK2 complex activity." (PMID 19684852, 2009). "This suggests that unlike in normal cells where CDK4/6 can rapidly compensate for pharmacologic inhibition of CDK2 to drive ongoing proliferation, this is not the case in CCNE1-amplified cancers." (PMID 38047585, 2024). "Although CDKN3 has a negative adjustment effect on CDK1 and CDK2, the carcinogenic effect of CDKN3 is abnormally expressed, which is related to a variety of human cancers." (PMID 36147496, 2022). "It has been shown that Nic induces downregulation of CDK2 and CDK4, but not CDK7, cyclin D2 or cyclin H in other cancer types." (PMID 36304150, 2022). "Using combined pan-cancer studies, moderately positive correlations of CCT2 mRNA were found with MYC, CDK2, CDK4, CCNE1 but not CCND1 (slight negative correlation)." (PMID 33996588, 2021). "In addition, CDK2 positively regulates HIF-1α transactivity in cancer cells, and it was postulated that CDK2 could uncouple the transcriptional and non-transcriptional functions of HIF-1α in a manner analogous to the well-characterised mechanism involving cMYC and SKP2." (PMID 33383924, 2020).
cancer (continued). "Notably, an increased reliance on CDK2 may be a therapeutic vulnerability, suggesting an opportunity for CDK2 inhibitors in cancers that delete CDKN1B (although, unlike CDK4/6 inhibitors, CDK2 inhibitors have not yet been successful in the clinic due to high toxicity)." (PMID 33166394, 2020). "The investigated compounds tested in vitro against human cancer cell lines (MCF-7, K-562) and CDK2/E as well as Abl protein kinases inhibitors showed no significant anticancer activity." (PMID 31948129, 2020). "Unlike silencing WEE1 in human cancer cell lines, where DDR depends on CDK2 but not CDK1, we demonstrate that DNA damage in Cdk1AF MEFs depends on CDK1 and not on CDK2." (PMID 30190546, 2019). "For example, CDK2−/− mice are viable, and silencing of CDK2 had no significant impact on proliferation in some cancer cells." (PMID 25557169, 2015). "The effects of cyclin-dependent kinase 2 (CDK2) silencing and chemical inhibition were tested in cancer cells with and without CCNE1 amplification." (PMID 22433433, 2012). "Notably, engineered gain of CDK2, but not CDK9 expression, reversed emergence of cancer cells with chromosome rings or multipolarity, despite CYC065-treatment." (PMID 38031910, 2023). "However, related genes (e.g., CDK1, CDK2, SMARCB1, SMARCA4) were excluded from the present study because they are either well-known genes in cancer or did not have significantly altered messenger RNA (mRNA) levels." (PMID 29712898, 2018). "In the cancer cells, Rb is phosphorylated on CDK2 phosphorylation sites as well as CDK4 phosphorylation sites, whereas our data showed that Rb phosphorylation on the CDK2-specific phosphorylation site, threonine 821, was not induced by TNF-α treatment (day 6)." (PMID 24302570, 2013). "Furthermore, cancer cells harbouring CCNE1 gene amplification displayed a higher sensitivity to the CDK1, CDK2 and CDK9 small molecule inhibitor AZD5438 than cancer cells lacking CCNE1 gene amplification (t-test, P = 0.019)." (PMID 22433433, 2012). "The results indicated that anti-cancer effect of GTs might be related to histone acetylation and interphase of mitotic cell cycle by regulating general control non-derepressible 5 (GCN5) and cyclin-dependent kinase-2 (CDK2), respectively." (PMID 27213329, 2016).
tumor (624 papers, 1999 to 2026). "CDK2 expression is linked to higher tumor purity and CAF infiltration, but lower immune score and reduced levels of antitumor immune cells, including B cells and M1 macrophages." (PMID 41614894, 2026). "The combined therapy of lenvatinib with CDK2 inhibitor significantly induced tumor cell senescence and caused tumor growth suppression in vitro and in vivo, demonstrating an effective strategy in lenvatinib‐resistant ATC." (PMID 39716890, 2025). "Overexpression of CCNE1, the gene encoding cyclin E, is common in various tumor types and contributes to aberrant CDK2 activation, rendering tumor cells dependent on this complex for proliferation." (PMID 41007649, 2025). "In the present study, we found that CDK2 was associated with lenvatinib resistance, and CDK2 inhibition combined with lenvatinib was synergistic in anti‐tumor activity in ATC with high CDK2 expression." (PMID 39716890, 2025). "Mutations or abnormalities in components regulating CDK2, or in its upstream activators such as Ras, can sustain the active state of CDK2, promoting tumor growth and progression." (PMID 38532893, 2024). "Tumours showing a combined high nuclear and high cytoplasmic CDK2 expression were significantly linked with serous cancer (adjusted p value = 0.007) and a high grade (adjusted p value = 0.02)." (PMID 38612869, 2024). "In turn, this resulted in a significant reduction in CDK2 and cyclin E kinase activities, ultimately causing tumor cells to arrest at the G1 phase and inhibiting the growth of LNCaP cells." (PMID 39055491, 2024). "Here, we provide the first clinical evidence that CDK2 overexpression in CDK4/6-negative tumours is significantly linked with aggressive tumours and poor survival compared to tumours with low CDK2 and highly CDK4/6-expressing tumours." (PMID 38732271, 2024). "In the multivariate analysis, CDK2 was independently associated with a poor survival outcome (p = 0.02) in relation to tumour size and stage." (PMID 38732271, 2024). "CDK2 inhibition phenocopied genetic loss of Mybl2 and significantly decreased in vivo tumor growth associated with enrichment of DNA damage." (PMID 39113611, 2024). "As such, knockdown of FOXM1 increases the expression of p16INK4a and other CDK inhibitors, whereas FOXM1 overexpression suppresses their transcription and causes elevated activity of tumor-promoting CDK2 and CDK4/6." (PMID 37686402, 2023). "Our data suggest that nifuroxazide enhances the anticancer effects of palbociclib in TNBC by uncoupling SASP production from senescence-associated cell cycle exit and inhibiting CDK2 to promote tumor senescence." (PMID 37752122, 2023). "Since we have portrayed elevated cell proliferation process as the distinctive feature of GBMs, we then tried to illustrate the potential association between enhanced CDK2 activity and fast tumor cell growth in GBMs." (PMID 36720864, 2023). "Another nine hypermethylated CpG sites can reduce the expression of CDK2AP1, which encodes cyclin-dependent kinase 2 (CDK2), which is important in the reducing of cell proliferation, contributes to cell cycle termination, and is a known tumor suppressor." (PMID 35163587, 2022). "Previous studies have also reported strong associations of EIF4A3 with different cell cycle regulatory genes (CDK1 and CDK2), tumor-associated transcription factors, chemokine signaling pathways and spliceosome signaling pathways." (PMID 35139874, 2022). "To this end, we investigated associations of STAT3/CDK2/4/6 expressions with tumor-immune infiltration across the TCGA dataset." (PMID 33668805, 2021). "As Cdk2-deficient tumours also displayed low expression of some DNA repair genes, we cannot exclude that distinct functions of CCNE1 for DDR require CDK2." (PMID 34830835, 2021). "Arsenic trioxide causes tumour cell differentiation, triggers cell apoptosis and induces G1 and/or G2-M phase arrest via down-regulation of CDK2, CDK6, cyclin D1, Cyclin E, Cyclin A and Cdc2 kinase." (PMID 32002123, 2020).